TNF (tumor necrosis factor)
Diseases named in the same sentence as TNF in open-access papers (continued):
Sharing a sentence is not in itself a finding about the gene and the disease.
heart failure (continued). "Although heart failure cases have been reported in patients treated with TNF-α inhibitors, the risk of new onset of heart failure in patients under age 50 receiving etanercept or infliximab is low." (PMID 33053859, 2020). "Heart failure development is associated with an elevated expression of multiple pro-inflammatory cytokines, and both IL-6 and TNFα are associated with left ventricular remodeling and myocyte hypertrophy." (PMID 32271823, 2020). "Elevated levels of TNF-α in plasma have been implicated in various cardiovascular diseases, including heart failure and myocardial infarction." (PMID 32686827, 2020). "Use of TNF inhibitors cause a decrease in TNF- α levels and can so prevent cardiac remodeling and heart failures." (PMID 33193432, 2020). "It is possible that diabetic cardiomyopathy differently affects men and women, as the latter present higher risk to develop heart failure and a higher plasmatic level of the pro-inflammatory cytokine, tumor necrosis factor alpha (TNFα), than men." (PMID 30792662, 2019). "So far, it has been found that inflammatory cytokines associated with the heart failure mechanism include TNF-α, IL-6, IL-8, IL-10, IL-1α, IL-1β, IL-2, TGF-β, and IFN-γ." (PMID 31275453, 2019). "Anti-TNF alpha therapy is contraindicated in patients with classes III-IV New York Heart Association heart failure." (PMID 29622900, 2018). "TNF-α also triggers cardiomyocyte apoptosis, which eventually results in considerable myocyte loss leading to the development of heart failure." (PMID 29511093, 2018). "Circulating IL-10 levels were diminished in patients with heart failure, while it has been reported that elevated levels of IL-10 and TNF-α was associated with an increased risk of mortality." (PMID 30177883, 2018). "Persistent inflammation, with chronically elevated concentrations of proinflammatory cytokines like TNF-α, ET-1, and IL-6, plays a pathogenic role in heart failure." (PMID 29093735, 2017). "Increased levels of cytokines, especially IL-6 and tumor necrosis factor alpha (TNFα), are also associated with frailty, decreased muscle endurance, and heart failure." (PMID 27148509, 2016). "Rather, these cytokines correlate with mortality in heart failure and TNFα over-expression causes severe heart failure in animal models." (PMID 26070197, 2015). "Already two decades ago, the observation of increased tumor necrosis factor (TNF) levels in patients with heart failure linked inflammation to CVDs." (PMID 24611063, 2014). "Our observations reconciled with those findings concerning that TNF-α impaired fatty acid oxidation in the heart through activation of NF-κB, which underlies cardiac dysfunction and heart failure in metabolic diseases." (PMID 25045214, 2014). "In the Framingham Heart Study, increased inflammatory markers, such as CRP, interleukin-6 and TNFα levels, were able to identify asymptomatic older subjects in the community who were at high risk for the future development of heart failure." (PMID 25142635, 2014). "Recently, other TNFSF/TNFRSF members than TNF have been implicated in the pathophysiology of heart failure." (PMID 24611063, 2014). "Tumor necrosis factor (TNF) has been firmly established as a pathogenic factor in heart failure, a significant socio-economic burden." (PMID 24611063, 2014). "TNF-α is a proinflammatory cytokine that has been implicated in the pathogenesis of cardiovascular diseases, including I/R injury, heart failure, and cardiac allograft rejection." (PMID 24167735, 2013). "The inflammatory cytokines IL-6 and TNF-α, are known to promote LV dysfunction and play a pathogenic role in heart failure and DCM." (PMID 24086665, 2013). "Among patients with Chagas' cardiomyopathy who also have overt heart failure, particular TNF-α genotypes have been associated with a significantly shortened survival." (PMID 23451183, 2013). "A significant association was observed between TNF-α-positive cells and the presence of heart failure (P = 0.040)." (PMID 22811738, 2012).
heart failure (continued). "TNF is a cytokine associated with inflammatory properties that also has been associated with severity and risk stratification of heart failure in a number of studies." (PMID 22588803, 2012). "In an in-vivo study in rats, it has been observed that the progression of experimentally induced heart failure subsequent to myocardial infarction was associated with a decrease in IL-10/TNF-α ratio." (PMID 21949832, 2011). "Exacerbated TNF and sTNFR1 expression is related to systemic and cardiac glutathione deficiency in animal models of heart failure, and in advanced heart failing patients." (PMID 19319187, 2009). "It has been reported that p38 activation has a apoptotic and profibrotic effect by inducing apoptosis and the release of TNF-α and IL-6 in cardiomyocytes, which are closely associated with the development of fibrosis, adverse cardiac remodeling, and heart failure." (PMID 40610735, 2025). "In addition, proinflammatory cytokines (TNF-α, IL-1β, etc.)produced by adipose tissue have been associated with a poor prognosis of heart failure." (PMID 40507126, 2025). "TNF-α, in particular, has been strongly associated with the progression of heart failure." (PMID 40787514, 2025). "Furthermore, TNFα-induced apoptosis is associated with LV dysfunction in pacing-induced heart failure." (PMID 40650199, 2025). "Furthermore, previous studies have shown that RDW is associated with the levels of interleukin 6 in heart failure and tumor necrosis factor in coronary artery lesions of Kawasaki disease." (PMID 36920980, 2023). "TNF is usually considered as a cardiotoxic factor, the reason why anti-TNF therapy may increase heart failure risk is still unclear." (PMID 38029150, 2023). "Moreover, TNF-α and IL-1β contribute to cardiac hypertrophy, forming another risk factor for heart failure." (PMID 38270118, 2023). "This might be the reason that TNF-alpha antagonism causes an increased risk of heart failure hospitalization." (PMID 35915691, 2022). "In this review, we lay forth the current understanding of how TNF causes heart failure." (PMID 35813433, 2022). "Studies suggest that TNF-α inhibits downregulation of the inflammatory response during ischemia, and that ongoing inflammation leads to further damage of cardiomyocytes, increasing the long-term risk of heart failure." (PMID 36399460, 2022). "Increased TNFα and iNOS levels associated with heart failure." (PMID 35548775, 2022). "Lipid-lowering drugs (methotrexate from the non-biologic DMARDs family as well as biologic DMARDs such as anti-TNF) were all associated with a lower CV risk; however, anti-TNF medication can decrease cardiac compliance and promote heart failure in patients with previously diagnosed chronic HF." (PMID 35206926, 2022). "Consequently, anti-TNF therapy remains contraindicated in IBD patients with class III-IV New York Heart Association (NYHA) heart failure." (PMID 36289474, 2022). "However, these guidelines specifically highlight the risk of heart failure caused by TNF-α antibodies." (PMID 35844550, 2022). "This may be due to a greater inhibition of TNFR2 caused by the higher dose of a TNF alpha inhibitor, which may have exacerbated cardiac failure." (PMID 34660128, 2021). "TNF-α is also associated with the propagation of heart failure." (PMID 33671607, 2021). "It has been reported that the levels of IL-6, CRP, and TNF-α are important indicators of MI-related cardiac complications, and these inflammatory cytokines have been reported to be closely associated with the occurrence of heart failure." (PMID 34123595, 2021). "Although elevated circulating TNF‐α is considered a biomarker for cardiovascular disease, specific cardiomyocyte expression of TNF‐α has been associated with more progressive forms of heart failure including systolic dysfunction, whereby the relative gene dosage is proportional to disease severity." (PMID 34713972, 2021).
heart failure (continued). "Moreover, SARS-CoV-2 infection is known to cause cardiac damage and dysfunction in 20–30% of hospitalized patients and in the absence of infection well known inflammatory mediators such as TNF are associated with heart failure." (PMID 34439792, 2021). "Moreover, myocardial remodelling can cause cardiomyocyte apoptosis through the production of TNF‐α in large amounts and lead to heart failure." (PMID 33295096, 2021). "In a cohort of 981 patients with coronary heart disease enrolled in the Heart and Soul study, HCV seropositivity was associated with changes in levels of CRP, TNF‐α, IL‐6 increased Framingham risk scores, and hospitalizations due to clinical cardiac failure and death." (PMID 31785111, 2020). "Notably, low concentrations of TNF-α produces a cardioprotective effect, while increased levels of TNF-α have been associated to heart failure and diastolic dysfunction, and is positively correlated to the severity of the diseases." (PMID 31489895, 2019). "Additionally, TNFα induces mitochondrial ROS production in cardiac myocytes that is associated with mitochondrial DNA damage favoring the progression of heart failure." (PMID 30935055, 2019). "TNF is associated with disease progression to cardiac failure in chagasic patients, and genetic polymorphisms in this gene may be associated with protection during infection." (PMID 29590257, 2018). "In addition, TNF-α and IL-1β induce cardiomyocyte hypertrophy, which is another independent risk factor of heart failure." (PMID 29511093, 2018). "Tumor necrosis factor and lnterleukin-6 are elevated in heart failure patients, the former is associated with the activation of coagulation system and the latter has been shown to be associated with procoagulant tissue factor in heart failure patients." (PMID 28450810, 2017). "Thus, GSPE can effectively inhibit the inflammatory indicator TNF-α in the pathological process of secondary myocardial cell apoptosis and cardiac insufficiency caused by MT to enhance heart protection from the upstream." (PMID 28294148, 2017). "In the third hypothesis, the state decreased cardiac output in heart failure causes systemic tissue hypoxia with subsequent systemic inflammation, which in turn may be the primary stimulus for increased TNF-α production." (PMID 28674538, 2017). "Mechanically, the weight loss-related to heart failure has been explained as part of its metabolic impairment, namely insulin resistance, global anabolic blunting and catabolic overactivity due to catecholamine, TNF-alpha, and natriuretic peptides release." (PMID 29075334, 2017). "Additionally, higher plasma levels of TNF-α and IL-6 have been shown to be associated with LV dysfunction in patients with heart failure." (PMID 27977796, 2016). "In a meta-analysis published in 2011, comprising 20 previous publications, Westlakeet al. summarized the potential effects of anti-TNF-α inpatients with psoriatic arthritis not only on MACE (including heart failure), butalso on the risk of developing cardiovascular disease again." (PMID 28099601, 2016). "Among the several potential causes of this association, inflammatory cytokines as TNF-α as well as IL-6 have been shown to be predictors in heart failure; these cytokines may impact bone marrow function and iron metabolism." (PMID 24660068, 2014). "Moreover, we put in light a TNF-α-independent beneficial effect of pentoxifylline in the VEETKO mice suggesting a therapeutic potential for pentoxifylline in a subpopulation of heart failure patients at higher risk." (PMID 24523936, 2014). "Importantly, the number of TNF-producing cells in the cardiac tissue is associated with the presence of heart failure in CD patients." (PMID 25140115, 2014). "Cleavage of membrane ACE2 by up-regulated proteases in advanced heart failure, such as tumor necrosis factor-∝ ADAM17 may deplete local myocardial ACE2 causing LV remodeling." (PMID 23630610, 2013).
heart failure (continued). "Interestingly, production of these factors is upregulated in response to inflammatory mediators associated with heart failure such as TNF-alpha." (PMID 20398245, 2010). "Elevated TNFα concentrations may be important in the pathogenesis and perpetuation of heart failure by modulating systemic metabolism, causing apoptosis and having a negative inotropic effect." (PMID 20224758, 2009). "Given the established role of cytokines such as interleukin-1, interleukin-6, and tumor necrosis factor alpha in the pathophysiology of heart failure, it is plausible that the symptomatic relief associated with MSCs may be, at least partly, secondary to their immunomodulatory capacity." (PMID 40422568, 2025). "Similarly, SDF-1, implicated in ischemic heart disease and heart failure, may exacerbate TNF-α-induced cardiomyocyte death and dysfunction." (PMID 39940718, 2025). "Although monocytes are considered an essential component of the inflammatory cascade in heart failure, relevant evidence until now has been based mainly on studies regarding monocyte-derived cytokines implicated in the pathogenesis of heart failures, such as TNF and IL-6." (PMID 37189647, 2023). "Consequently, IL-6 and TNF-α are associated with heart failure and all-cause mortality." (PMID 36729923, 2023). "Moreover, AUGIB is always accompanied by systemic inflammation and causes the release of cytokines such as tumor necrosis factor-α and interleukin-1, which could potentiate subclinical heart failure and myocardial dysfunction." (PMID 36568536, 2022). "Finally, physical training programs implementations in patients destined for activity restriction such as heart failure resulted in decreased circulatory concentrations of proinflammatory cytokines including plasma TNF-a and IL-6, both implicated in preterm labor." (PMID 29889906, 2018). "Small-scale studies assessing methotrexate and thalidomide in heart failure have shown mixed results, with variable effects on functional class, 6-min walking distance, and TNF-α levels." (PMID 40828623, 2025). "Studies confirmed the role of TNF-α in the pathophysiology of heart failure in RA: patients treated with anti-TNF agents less frequently developed HF (p = 0.03)." (PMID 41010664, 2025). "Since then, multiple studies have emphasized the prognostic relevance of inflammatory markers such as C-reactive protein (CRP), tumor necrosis factor-alpha (TNF-α), and interleukin-6 (IL-6) in heart failure." (PMID 40869365, 2025). "Several studies have reported that n–3 PUFA supplementation reduces inflammatory markers in patients with heart failure, including TNF-α, IL–1, and IL–6." (PMID 39805484, 2025). "As heart failure progresses, pronounced inflammatory responses, such as the overproduction of TNF-α and IL-6, result in damage to the vascular walls and reduced myocardial efficiency." (PMID 39805484, 2025). "Since 1990, studies have confirmed elevated levels of various inflammatory mediators, including TNF-α, IL-6, IL-1β, IL-18, and immune antigens, in the plasma of heart failure patients." (PMID 40671145, 2025). "However, TNF-α inhibition may worsen cardiovascular risk in heart failure patients." (PMID 40661082, 2025). "The plasma level of tumor necrosis factor alpha (TNF-α) is high in patients with HF, and some cytokines (such as IL-1β and IL-6) are also implicated in the process of heart failure." (PMID 39796168, 2025). "Studies suggest that omega-3 supplementation effectively lowers circulating levels of inflammatory cytokines, particularly in patients with heart failure (HF), by reducing TNF-α, IL-6, and C-reactive protein (CRP) levels." (PMID 40427653, 2025). "In the heart, it seems that TNF-α contributes to ischemia/reperfusion injury, post-myocardial infarction remodeling, and heart failure development making it a favorable target for cardioprotection." (PMID 38520533, 2025).
heart failure (continued). "The inflammatory cytokine levels (IL-1, IL-6, and TNF-α) are significantly higher in heart failure patients compared to the control group (p < 0.001 for all markers)." (PMID 40943854, 2025). "Previous studies have shown that a large number of inflammatory factors such as IL-6 and TNF-α are expressed in the serum of patients with heart failure." (PMID 39874368, 2025). "Simultaneously, in the insulin-resistant state of heart failure patients, the production of inflammatory factors such as tumor necrosis factor-alpha (TNF-α) and interleukin-6 (IL-6) increases." (PMID 40442740, 2025). "A systematic review and meta-analysis reported that omega-3 supplementation significantly lowered TNF-α and IL-6 levels in patients with heart failure, suggesting a potential role in controlling cardiovascular inflammation." (PMID 40427653, 2025). "Recognition of TNF’s role in the pathogenesis of heart failure led to early experimental trials in the 2000s that tested anti-TNF agents as a therapeutic option." (PMID 41155452, 2025). "Our recent meta-analysis also confirmed the reduction in tumor necrosis factor-α and interleukin-6 in patients with heart failure, after n-3 PUFA ingestion." (PMID 38777807, 2025). "The increase of IL-6 content can promote the apoptosis of cardiomyocytes, and TNF-α is an important index reflecting the degree of heart failure." (PMID 39874368, 2025). "Among anti-TNF-α agents, infliximab and etanercept have been evaluated in patients with heart failure and reduced ejection fraction (HFrEF)." (PMID 40828623, 2025). "Pro-inflammatory cytokines including tumor necrosis factor-α (TNF-α), interleukin-1 (IL-1), and interleukin-6 (IL-6) exhibit close associations with the pathogenesis of heart failure." (PMID 41526164, 2025). "They demonstrated that TNFα was significantly increased in both sera and heart tissue of the heart failure group, and these cardiomyocytes showed reduced activity of the mitochondrial respiratory chain enzyme complex." (PMID 40650199, 2025). "Treatment with high-dose LA&ALA significantly attenuated the expression of NT-ProBNP, NO, VCAM, VEGF, and TNF-α compared with the model group (p < 0.05), indicating an amelioration in heart failure symptoms." (PMID 41154077, 2025). "This study demonstrates that IL-1, IL-6, and TNF-α are significantly elevated in heart failure patients and strongly correlate with reduced LVEF, indicating their association with disease severity." (PMID 40943854, 2025). "taVNS has been shown to suppress pro-inflammatory cytokines such as TNF-α and IL-1β, thereby mitigating the chronic low-grade inflammation commonly observed in heart failure." (PMID 41584276, 2025). "Inflammatory cytokines are persistently elevated in patients with congestive heart failure, with TNF-α being a pivotal pro-inflammatory cytokine that exacerbates heart failure by counteracting the anti-inflammatory response and disrupting systemic homeostasis." (PMID 41268442, 2025). "Compared with HF group, IL-1β, IL-6 and TNF-α inflammatory factors in blood of rabbits with heart failure were decreased in different degrees after administration of dapagliflozin, and there were significant differences (P<0.05)." (PMID 39874368, 2025). "This is also the reason why the heart is also called a TNF-α-producing organ, especially during heart failure when there is a surge in secretion." (PMID 38261135, 2024). "TNF-α worsens heart failure by disrupting the mechanism that preserves homeostasis, leading to imbalance and suppressing anti-inflammatory responses." (PMID 39459589, 2024). "The levels of circulating TNF-α are accountable for the reduced expression of myocardial TNF-α receptors observed in heart failure." (PMID 38542544, 2024). "Tumor necrosis factor-alpha can contribute to cardiac fibrosis, heart failure, and various cancers by upregulating the COX-2/PGE2 axis." (PMID 39830670, 2024).